COPS7B (COP9 signalosome subunit 7B)
Description:
Component of the COP9 signalosome complex (CSN), a complex involved in various cellular and developmental processes. The CSN complex is an essential regulator of the ubiquitin (Ubl) conjugation pathway by mediating the deneddylation of the cullin subunits of SCF-type E3 ligase complexes, leading to decrease the Ubl ligase activity of SCF-type complexes such as SCF, CSA or DDB2.
Synonyms: SGN7b; CSN7B
Tractability: PROTAC: ubiquitination databases record sites on it; its protein half-life has been measured.
Gene: Protein-coding gene on chromosome 2 (231,781,671 to 231,809,254, forward strand). Ensembl gene ENSG00000144524.
Subcellular location: Cytoplasm; Nucleus
Subcellular location (Human Protein Atlas): Nucleoplasm
Pathways (Reactome):
DNA Repair: DNA Damage Recognition in GG-NER; Formation of TC-NER Pre-Incision Complex
Metabolism of proteins: Neddylation
Vesicle-mediated transport: Cargo recognition for clathrin-mediated endocytosis
Gene Ontology:
Molecular function: protein binding
Biological process: protein deneddylation; regulation of protein neddylation; COP9 signalosome assembly
Cellular component: COP9 signalosome; nucleoplasm; cytosol; cytoplasm; nucleus; protein-containing complex
Genetic constraint (gnomAD): Loss-of-function variants: 9 observed, 30.38 expected, observed/expected ratio (o/e) 0.3, 90% interval 0.18 to 0.52. The upper end of that interval is the gene's LOEUF score, 0.52, which puts it in group 2 of 6, group 1 being the genes least tolerant of losing a copy. Missense variants: 236 observed, 325.13 expected, observed/expected ratio (o/e) 0.73, 90% interval 0.65 to 0.81. Synonymous variants: 118 observed, 132.82 expected, observed/expected ratio (o/e) 0.89, 90% interval 0.76 to 1.03.
Homologues: Orthologues: dog COPS7B (99% identical), guinea pig COPS7B (98% identical), mouse Cops7b (98% identical), macaque COPS7B (98% identical), rat Cops7b (98% identical), tropical clawed frog cops7b (86% identical), chimpanzee COPS7B (81% identical), rabbit COPS7B (81% identical), pig COPS7B (81% identical), Drosophila melanogaster CSN7 (44% identical). Paralogues in human: COPS7A (58% identical), EIF3M (19% identical).
Diseases named in the same sentence as COPS7B in open-access papers:
COPS7B is named in the same sentence as 2 diseases in open-access papers, as found by Europe PMC text mining. Sharing a sentence is not in itself a finding about the gene and the disease. The quoted sentences say what the papers report.
cancer (2 papers, 2022). A tumor composed of atypical neoplastic, often pleomorphic cells that invade other tissues. "Some genes always selected by each method were found (COPS7B, DONSON, GTF2E2, HAUS8, PRH2, and ZNF18) with known roles in cancer formation and progression." (PMID 35954157, 2022).
COPS7B also shares sentences with these, for which no sentence is quoted: renal cell carcinoma (1 paper).